IL2RG (interleukin 2 receptor subunit gamma)
Diseases named in the same sentence as IL2RG in open-access papers (continued):
Sharing a sentence is not in itself a finding about the gene and the disease.
severe combined immunodeficiency (56 papers, 2012 to 2026). Severe combined immunodeficiency (SCID) comprises a group of rare monogenic primary immunodeficiency disorders characterized by a lack of functional peripheral T lymphocytes resulting in early-onset severe respiratory infections and failure to thrive. "The next notable advance in immunodeficient mice came with the introduction of X-linked severe combined immunodeficiency resulting from a null allele of the IL-2 receptor common γ-chain (IL2Rg, CD132)." (PMID 37859310, 2024). "For example, two different IL2RG variants have been reported to cause an X-linked severe combined immunodeficiency in dogs (OMIA: 000899-9615), and each has only been detected in a single breed." (PMID 38535207, 2024). "Two novel pathogenic variants of IL2RG were identified by CES from patients with severe combined immunodeficiency (SCID)." (PMID 37325673, 2023). "Severe chronic HPV disease is associated with severe combined immunodeficiency (SCID) caused by IL2RG (interleukin 2 receptor subunit γ) or JAK3 deficiency." (PMID 36960048, 2023). "This is in contrast with existing data on female carriers of some other X-linked inborn errors of immunity such as IL2RG-deficient severe combined immunodeficiency and CD40L deficiency, who appear to be asymptomatic." (PMID 37620741, 2023). "A patient (P18) was diagnosed with severe combined immunodeficiency (SCID) due to an IL2RG mutation." (PMID 33743629, 2021). "In this study, we report a 4-month-old boy with T−B+NK− severe combined immunodeficiency (SCID) due to a novel mutation in exon 2 of IL2RG, the gene encoding the interleukin (IL) common gamma chain (γc) of the cytokine receptors for IL-2, IL-4, IL-7, IL-9, IL-15, and IL-21." (PMID 35498802, 2022). "X-linked severe combined immunodeficiency (X-SCID), caused by mutations in the interleukin-2 receptor gamma chain (IL2RG) gene, is one of the most common forms of SCID, accounting for approximately 50%–60% of cases." (PMID 41164818, 2025). "We report a case of T-B+NK+ severe combined immunodeficiency disease (SCID) caused by IL2RG gene mutation (NM_000206.3 [IL2RG]: c.925-2A > G)." (PMID 39450341, 2024). "X-linked severe combined immunodeficiency (X-SCID), caused by mutations in the interleukin-2 receptor gamma chain (IL2RG) gene, is a common type of SCID, accounting for approximately 50% to 60% of cases." (PMID 39176082, 2024). "Patients with severe combined immunodeficiency (SCID) caused by LOF mutations of IL2RG or JAK3 who undergo hematopoietic stem cell transplantation do not reconstitute a normal pool of peripheral ILC and NK cells." (PMID 36736301, 2023). "The most extreme syndrome of lymphocyte dysfunction, severe combined immunodeficiency (SCID), arises from mutations in a number of genes: IL2RG, RAG1, RAG2, ADA, JAK3, and IL7RG." (PMID 36839582, 2023). "Mutations of the IL2RG gene, which encodes for the interleukin-2 receptor common gamma chain (γC, CD132), can lead to X-linked severe combined immunodeficiency (X-SCID) associated with a T−B+NK− phenotype as a result of dysfunctional γC-JAK3-STAT5 signaling." (PMID 35052377, 2021). "For instance, a mutation in interleukin-2 receptor subunit gamma (IL2RG) causes severe combined immunodeficiency (SCID)." (PMID 34858409, 2021). "The first proof of concept was obtained using ZFN on primary T cells ex vivo to replace interleukin-2 receptor subunit gamma (IL2RG), whose mutational inactivation causes X-linked severe combined immunodeficiency (X-SCID)." (PMID 34713234, 2020). "To test the activities of SaCas9 LVLPs on endogenous targets, we prepared IDVL expressing sgRNA targeting human IL2RG, mutation of which causes X-linked severe combined immunodeficiency (SCID-X1)." (PMID 30759231, 2019).
severe combined immunodeficiency (continued). "Severe combined immunodeficiency (SCID), caused by mutations in genes affecting lymphocyte development or function, such as IL-2RG, RAG1 and/or RAG2, and PRKDC, accounts for the most severe phenotypes among primary immunodeficient patients." (PMID 29593714, 2018). "For instance, disruption of IL2RG in pigs recapitulates the phenotype of X-linked severe combined immunodeficiency (SCID) patients much closer than Il2rg knockout rodent models." (PMID 27118081, 2016). "Mutations in IL2RG cause X-linked severe combined immunodeficiency (X-SCID) and a broad spectrum of related phenotypes ranging from typical SCID to leaky or atypical presentations, sometimes mimicking common variable immunodeficiency or immune dysregulation syndromes." (PMID 41909668, 2026). "In addition, it is well known that approximately one-third of X-linked severe combined immunodeficiency (X-SCID) cases have a positive family history, implying that the rest of the two-thirds arise from de novo mutations in the IL2RG gene." (PMID 41011036, 2025). "Hashikawa and his team also succeeded in generating a stable strain of rabbits with X-linked severe combined immunodeficiency (X-SCID), harboring a phenotype that encompasses hyperplasia of the thymus and the loss of B and T cells by targeting the Il2rg gene via the CRISPR-Cas9 system." (PMID 36429042, 2022). "The mortality rate was the highest in patients with non-syndromic combined immunodeficiency (51.7%, median age: 3.5 years) and particularly in patients with mutations in specific genes associated with this phenotype (RFXANK, RAG1, and IL2RG)." (PMID 34052995, 2021). "We present here a male young infant with X-linked severe combined immunodeficiency (MIM#300400) due to the novel nonsense variant of IL2RG (interleukin 2 receptor, gamma; MIM#308380), NM_000206.2(IL2RG):c.820_823dup p.Ser275Asnfs*29." (PMID 34796149, 2021). "The classical example is severe combined immunodeficiency (SCID) with defects in T cells, B cells, and NK cells caused by defects in IL2RG, RAG1/2, ADA, JAK3, and IL7R genes, in which an increased risk of disseminated VZV infection has been well-recognized for many years." (PMID 32495195, 2020). "Seven founder knockout rabbits (F0) and three male IL2RG null (−/y) F1 animals demonstrated severe combined immunodeficiency (SCID), characterized by absence or pronounced hypoplasia of the thymus and splenic white pulp, and absence of immature and mature T and B-lymphocytes in peripheral blood." (PMID 29593714, 2018). "X-linked severe combined immunodeficiency (X-SCID), caused by mutations in the gamma-chain gene of the interleukin-2 receptor (IL2RG), is a prevalent form of SCID characterized by recurrent and fatal opportunistic infections that occur early in life." (PMID 39176082, 2024). "Switching to humans, ZFNs were quite effective in modifying interleukin-2 receptor subunit gamma (IL2RG), noting that patients with X-linked severe combined immunodeficiency (X-SCID) have a defective IL2RG gene." (PMID 36429042, 2022). "X-linked severe combined immunodeficiency (SCID-X1): Mutations in γ chain (γc) encoding interleukin 2 receptor subunit gamma (IL2RG) gene, a major subunit of encoding for common γ chain (γc), leads to SCID-X1." (PMID 34503562, 2021). "Genetic defects in IL2RG or JAK3 can cause the phenotype of severe combined immunodeficiency (SCID) with absent T- and non-functional B-lymphocytes (T-B+ SCID)." (PMID 41863562, 2026). "Mutations in genes that affect the development or function of T and B cells [DCLRE1C(ARTEMIS), ZAP70, RAG1/2, IL2RG, ILRA7, LIG4, JAK3, ADA] can result in intestinal inflammation along with recurrent infections from severe combined immunodeficiency (SCID)." (PMID 34122435, 2021).
severe combined immunodeficiency (continued). "To evaluate the effect of XRC treatment on editing in long-term engrafting HSCs, we transplanted edited SC SC HSPCs and SC XRC HSPCs into immunodeficient non-obese diabetic (NOD) severe combined immunodeficiency (SCID) Il2rg−/− (NSG) mice." (PMID 32877675, 2020). "To determine the long-term engraftment potential of TRIAMF treated HSPCs, we injected untreated HSPCs and TRIAMF treated HSPCs with or without RNPs into sub-lethally irradiated non-obese (NOD)/severe combined immunodeficiency (SCID)/Il2rg−/− (NSG) mice." (PMID 30389991, 2018). "The IL2RG locus is a safe harbor for transgene expression in NSCs because it is not expressed in NSCs or any NCS progeny and people with mutations in the IL2RG, although have a devastating severe combined immunodeficiency (SCID-X1) have no neurologic problems." (PMID 31132746, 2019). "A pig model with an interleukin-2 receptor subunit-gamma (IL2RG) deletion was successfully developed with T cells and natural killer (NK) cells in the absence of a thymus in order to mimic human Severe Combined Immunodeficiency (SCID)." (PMID 30169503, 2018).
X-linked severe combined immunodeficiency (35 papers, 2009 to 2026). "X-linked SCID (X-SCID) caused by interleukin 2 receptor gamma (IL2RG) gene mutations is the most common form of SCID." (PMID 39789600, 2025). "Mutations in the IL2RG gene cause X-linked severe combined immunodeficiency (X-SCID), which is a life-threatening rare disease." (PMID 40491749, 2025). "Mutations in IL2RG cause X-linked severe combined immunodeficiency (X-linked SCID), placing many women at risk of being carriers." (PMID 40869991, 2025). "The most prevalent type of SCID worldwide, accounting for approximately half of cases, is X-linked SCID, caused by mutations in the IL2RG gene that codes for the common gamma chain protein of the IL-2 receptor." (PMID 41011036, 2025). "In this study, we report a Japanese patient with X-linked SCID with a novel IL2RG variant identified through NBS." (PMID 39635533, 2024). "The most common genetic cause of SCID is variants in IL2RG (X-linked SCID), which encodes for the common gamma chain (γc) of the interleukin-2 (IL-2) receptor." (PMID 39635533, 2024). "Mutations in the IL2RG gene causing X-linked SCID were identified for the first time in 1993, and since then more than 200 mutations in the IL2RG gene have been recognized with the highest frequency of frameshift mutations." (PMID 37461086, 2023). "X-linked severe combined immunodeficiency (SCID-X1 or XSCID) is caused by mutations in IL2RG gene which encodes the common cytokine gamma chain (γc) subunit shared by multiple cytokine receptors (interleukin (IL)-2, 4, 7, 9, 15 and 21)." (PMID 36685559, 2022). "X-linked severe combined immunodeficiency (X-SCID) is a primary immunodeficiency that is caused by mutations in the interleukin-2 receptor gamma (IL2RG) gene." (PMID 36553615, 2022). "Mouse studies used IL2rg gene disruption to create a model of x-linked severe combined immunodeficiency (X-SCID), where the immunodeficient phenotypes are characterized by near complete lack of T cells, B cells, and NK cells." (PMID 32316187, 2020). "Specifically, IL2RG mutation results in X-linked severe combined immunodeficiency (XSCID), characterized by profound defects in cellular and humoral immunity in humans." (PMID 27809915, 2016). "IL2RG encodes the common gamma chain (γc), and mutations in IL2RG lead to X-linked severe combined immunodeficiency (XSCID), which is characterized by profound defects in cellular and humoral immunity in humans." (PMID 24130776, 2013). "The IL2RG gene encodes the interleukin-2 receptor γ chain (IL-2Rγ), and mutations in this gene cause X-linked severe combined immunodeficiency (X-SCID)." (PMID 19725963, 2009). "However, the most common type is X-linked SCID caused by mutations in the interleukin 2 receptor subunit gamma (IL2RG) gene." (PMID 38644403, 2024). "X-linked severe combined immunodeficiency is caused by IL2RG gene mutation." (PMID 37461086, 2023). "However, we observed that the most common type of SCID associated with HLH was IL2RG defect (X-linked SCID)." (PMID 35812426, 2022). "Importantly, four patients had dual diagnoses with glucose-6-phosphate dehydrogenase (G6PD) deficiency: X-linked SCID (IL2RG), C6 deficiency (C6), IPEX syndrome (FOXP3), DiGeorge syndrome (TBX1)." (PMID 35757720, 2022). "IL2RG gene is associated with X-linked recessive severe combined immunodeficiency (X-linked SCID)." (PMID 34635152, 2021). "X-linked severe combined immunodeficiency (X-SCID) is an X-chromosome recessive primary immunodeficiency disorder caused by mutations in the interleukin-2 receptor gamma gene (IL2RG)." (PMID 36553615, 2022).
X-linked severe combined immunodeficiency (continued). "The similarity of IL-21 to IL-2, IL-4, and IL-15, suggests the possibility that IL-21 might share an important receptor on the common cytokine receptor γ chain (γc), encoded by IL2RG, the gene found to be mutated in humans with X-linked severe combined immunodeficiency (XSCID)." (PMID 33924897, 2021). "An example of this is the gene correction of IL2RG for X-linked severe combined immunodeficiency (SCID-X1), where IL2RG-corrected B and T cells have a strong advantage over IL2RG mutant cells in repopulating the thymus." (PMID 30577870, 2018). "One of the most common forms is X-linked SCID (X-SCID), which is caused by mutations in the IL2RG gene." (PMID 28963568, 2017). "X-linked Severe Combined Immunodeficiency (X-SCID), characterized by mutations in the IL2RG gene and resulting in impaired humoral and cell immunity, was effectively corrected by the HDR-mediated editing of IL2RG via ZFNs, for both in patient-derived HSCs and xenotransplantation mouse models." (PMID 36553489, 2022). "X-linked severe combined immunodeficiency (X-SCID) is an inherited and life-threatening primary immunodeficiency disorder (PID) that is caused by mutations in the interleukin-2 receptor gamma chain gene (IL2RG)." (PMID 35052377, 2021).
leukemia (20 papers, 2009 to 2025). A malignant (clonal) hematologic disorder, involving hematopoietic stem cells and characterized by the presence of primitive or atypical myeloid or lymphoid cells in the bone marrow and the blood. "To validate the xenograft model in oncology research, we injected human-derived leukemia cells (NALM6) intravenously into Il2rg/Rag2 KO rats and analyzed them using IVIS." (PMID 39731164, 2024). "To further evaluate the anti-leukemia activity of Apatinib in vivo, we established an acute lymphoblastic leukemia xenograft models by intravenous injection of Nalm6 cells into NODscid-IL2Rg−/− (NSI) mice." (PMID 29490645, 2018). "Last, in vivo anti-leukemia efficacy of DS/Cu was examined in patient-derived xenograft models of NOD-scid-IL2Rg-/- (NSI) mice, generated from the primary sample of an adult B-ALL patient with p16 deletion." (PMID 27203215, 2016). "An example is LMO2 and IL2RG cooperation in leukemia cases among X-SCID patients where insertional mutagenesis of LMO2 results in an increased growth advantage in the presence of IL2RG." (PMID 24886479, 2014). "The occurrence of leukemias in the SCID-X1 gene therapy trials also lends compelling support to the notion that IL2RG is oncogenic and a cooperating “hit” with LMO2." (PMID 19461887, 2009). "Thus, 2 of the AKXD murine leukemias with insertions at Lmo2 also contain insertions at Il2rg, a highly significant result (p = 1.34×10−9, see Text S1 for calculation)." (PMID 19461887, 2009). "In addition, tumor (7065) has insertions in Notch1 and Il2rg, suggesting that Il2rg might be able to cooperate with other T-cell oncogenes (i.e. Notch1) in leukemia induction." (PMID 19461887, 2009). "Our data show that Lmo2 and Il2rg cooperate but may not be sufficient for leukemia development and additional mutations contribute to leukemia development." (PMID 19461887, 2009). "The injection of 1 × 104 K562-GFP cells reconstituted leukemia in the NSI mice, whereas leukemia cells were under detectable in NOD-scid, IL2Rg−/−, scid, Rag2−/−, nude, or WT mice." (PMID 26022250, 2015). "The results showed that the expression of IL-2RG and IL-2RB mRNAs was decreased until reaching an undetectable level at 48 and 72 hours posttransduction, respectively, in K562-WT1-siRNA-GFP+ (WT1-siRNA) leukemia cells." (PMID 33110919, 2020). "This was demonstrated in early retroviral HSC IL2RG gene therapy for X-SCID patients, in which 4 of the 10 treated patients eventually developed leukemia, likely due to LMO2 activation induced by integration of the retrovirus and cooperation between the functions of LMO2 and IL2RG67." (PMID 29615705, 2018). "Although under dispute, the combinatorial effect of the IL2RG transgene in the development of the lymphoproliferative disease in the X-SCID trial has been discussed and recent work from Copeland and colleagues provides supportive evidence that IL2RG and LMO2 do cooperate in leukemia induction." (PMID 21994741, 2011). "Moreover, we assessed which components of the IL4R complexes that are expressed in c-Kit+ leukemia cells, and found that the Il4ra and Il2rg are expressed, but not Il13ra1." (PMID 28819278, 2018). "After the injection of 1 × 105 K562-GFP cells, successful reconstitution of leukemia was observed in NSI (medium survival time 27 days) and NOD-scid (medium survival time 48 days) mice, but not in IL2Rg−/−, scid, Rag2−/−, nude, or WT mice." (PMID 26022250, 2015). "We also provide additional evidence supporting the notion that IL2RG and LMO2 cooperate in leukemia induction but are not sufficient and require additional cooperating mutations." (PMID 19461887, 2009).
combined immunodeficiency (10 papers, 2018 to 2026). A broad classification of inherited disorders presenting at birth that affect both the cell-mediated and humoral aspects of the immune response. "Several cases with rare hemizygous IL2RG mutations and milder phenotypes, like X-linked combined immunodeficiency (CID) or common variable immunodeficiency (CVID), have been reported." (PMID 32072341, 2020).